CALCR (calcitonin receptor)
Diseases named in the same sentence as CALCR in open-access papers (continued):
Sharing a sentence is not in itself a finding about the gene and the disease.
Fabry disease (1 paper, 2025). Fabry disease (FD) is a progressive, inherited, multisystemic lysosomal storage disease characterized by specific neurological, cutaneous, renal, cardiovascular, cochleo-vestibular and cerebrovascular manifestations. "Methylation at −78,504 CpG of the calcitonin receptor gene indicates its role as a modifier of pain suppression in Fabry disease." (PMID 41150803, 2025). "Methylation at site 78,504 CpG in the promoter region of the calcitonin receptor gene could potentially serve as an epigenetic biomarker for individuals with more severe Fabry disease." (PMID 41150803, 2025). "Finally, a retrospective investigation of DNA methylation in the promoter region of the calcitonin receptor gene suggested that aberrant methylation of this gene could potentially serve as an epigenetic biomarker in individuals with Fabry disease on ERT." (PMID 41150803, 2025).
giant cell tumor (1 paper, 2025). A benign, intermediate, or malignant tumor that arises from the bone or soft tissue. "For instance, 2 newly identified human calcitonin receptor (CTR) variants, H-CTR5 and H-CTR6, are expressed in giant cell tumors, but their functional role remains unclear." (PMID 41268214, 2025).
Glucose intolerance (1 paper, 2023). Glucose intolerance (GI) can be defined as dysglycemia that comprises both prediabetes and diabetes. "In addition, conditional loss of the calcitonin receptor (Calcr) in proopiomelanocortin (POMC) neurons of the hypothalamus leads to increased body weight gain, increased adiposity, and glucose intolerance as a result of microglial IL-6 release." (PMID 36890585, 2023).
HIV-1 infection (1 paper, 2015). The type species of lentivirus and the etiologic agent of acquired immunodeficiency syndrome (AIDS). "Furthermore, HIV-1 infection induced formation of larger osteoclastst, enhanced the expression of mRNAs for three osteoclast specific marker molecules (tartrate-resistant acid phosphatase, cathepsin K, and the calcitonin receptor), and up-regulated osteoclast bone resorption activity." (PMID 25809599, 2015).
malignant glioma (1 paper, 2021). A grade III or grade IV glioma arising from the central nervous system. "Here, we discuss the proposal that the calcitonin receptor (CT Receptor), expressed in 76–86% of patient biopsies, is expressed by both malignant glioma cells and GSCs." (PMID 34571996, 2021).
medullary thyroid carcinoma (1 paper, 2017). "Calcitonin expression is a well-established marker for medullary thyroid carcinoma (MTC); yet the role of calcitonin receptor (CTR), its seven-transmembrane G-protein coupled receptor, remains to be established in C-cells derived thyroid tumors." (PMID 28929017, 2017).
non-small cell lung carcinoma (1 paper, 2022). A group of at least three distinct histological types of lung cancer, including non-small cell squamous cell carcinoma, adenocarcinoma, and large cell carcinoma. "It has been reported that CALCR expression is significantly upregulated in non-small-cell lung cancer and positively correlated with tumor invasion." (PMID 35422890, 2022).
osteonecrosis (1 paper, 2024). A none disease characterized by death of bone tissue due to a lack of blood supply. "It has also been demonstrated that miR-29 and miR-31-5p, which act on specific targets like RhoA and CALCR, promote osteonecrosis through programmed cell death." (PMID 38338876, 2024).
osteosarcoma (1 paper, 2022). A usually aggressive malignant bone-forming mesenchymal neoplasm, predominantly affecting adolescents and young adults.
renal carcinoma (1 paper, 2024). A carcinoma arising from the epithelium of the renal parenchyma or the renal pelvis. "Our results also suggested that JNK and STAT1 signaling were possible signaling pathways that contributed to CALCR-mediated renal carcinoma progression." (PMID 38985127, 2024). "Expression of CALCR in renal carcinoma tissues and para-carcinoma tissues was revealed by immunohistochemistry analysis." (PMID 38985127, 2024). "Conversely, the inhibition of CALCR on renal cancer cell apoptosis was remarkably attenuated by depleting CD44 expression (CALCR + shCD44 group vs. CALCR group, P < 0.001)." (PMID 38985127, 2024). "The transwell assays suggested that migratory capacity of renal cancer cells was apparently attenuated upon CALCR knockdown (P = 0.015, 786-O; P = 0.012, ACHN)." (PMID 38985127, 2024). "Relationship between CALCR expression and tumor characteristics in patients with renal carcinoma." (PMID 38985127, 2024). "Furthermore, the western blotting was used to investigate CD44 expression after CALCR knockdown in renal cancer cell, and we found that CD44 protein expression was inhibited upon CALCR depletion." (PMID 38985127, 2024). "Therefore, we selected CD44 as a key target for CALCR in renal cancer progression." (PMID 38985127, 2024). "We found that the phosphorylation of c-jun (P = 0.002) and STAT1 (P = 0.032) was significantly inhibited in CALCR-depleted cells compared to the respective control cells, reminding that c-jun and STAT1 related signaling pathways may be involved in CALCR induced renal carcinoma development." (PMID 38985127, 2024).
renal cell carcinoma (1 paper, 2024). "However, the molecular role of CALCR in renal cell carcinoma (RCC) is not well understood." (PMID 38985127, 2024).
rheumatoid arthritis (1 paper, 2006). A chronic, systemic autoimmune disorder characterized by inflammation in the synovial membranes and articular surfaces. "In our own studies involving analysis of synovial tissues from patients with rheumatoid arthritis we observed that, in addition to cathepsin K and TRAP expression, osteoclast-like cells in resorption lacunae at the bone-pannus interface express the calcitonin receptor (CTR)." (PMID 16613614, 2006).
virus infection (1 paper, 2012). "Nevertheless, amylin signaling through CalcR could decrease the viral infection and/or replication inside cells through a more complex mode of action." (PMID 22761571, 2012). "Regardless of CalcR expression, these cells remained non-permissive, ruling out a role of CalcR as a receptor for virus infection per se (data not shown)." (PMID 22761571, 2012).
tumor (14 papers, 2016 to 2026). "The western blot assays of tumor tissues showed that CALCR was effectively knocked down relative to the corresponding control group." (PMID 38985127, 2024). "By performing Ki-67 staining of tumor tissues, we found that the downregulation of CALCR accompanied a reduction in expression of Ki-67 (P = 0.016), implying the inhibition of CALCR on tumor cell proliferation." (PMID 38985127, 2024). "Other recent reports show variable expression of CALCR mRNA with expression in only a subset 12/42 or 115/152 of primary tumours." (PMID 30777055, 2019). "At the single-cell level, SLC16A14 was mainly expressed in malignant cells, and communication analyses suggested that CALCR-related signaling may mediate tumor-endothelial interactions and contribute to an immune-excluded microenvironment." (PMID 42136962, 2026). "Given the regulatory effect of CALCR on CD44 expression, we further explored whether the tumor promotion of CALCR required CD44 expression." (PMID 38985127, 2024). "In addition to its involvement in calcium regulation, there is evidence suggesting that CALCR acts as both tumor suppressor and an oncogene, influencing cell survival, apoptosis and cell cycle progression." (PMID 38985127, 2024). "Taken together, we demonstrated that CALCR was critical for in vivo tumor growth of RCC cells." (PMID 38985127, 2024). "Furthermore, the suppression of tumor growth induced by CALCR depletion was also observed in animal models." (PMID 38985127, 2024). "Moreover, CALCR depletion restricted in vivo tumor growth of ACHN cells." (PMID 38985127, 2024). "Taken together, these results suggested that CALCR and PTH1R played a critical role in tumor immune escape, which was involved in the carcinogenesis of GC." (PMID 35252217, 2021).
cancer (11 papers, 2016 to 2025). A tumor composed of atypical neoplastic, often pleomorphic cells that invade other tissues. "The calcitonin receptor (CALCR) is an essential protein for maintaining calcium homeostasis and has been reported to be upregulated in numerous cancers." (PMID 38985127, 2024). "Herein, we conducted an investigation of the alterations in CALCR expression in patients diagnosed with RCC and shed light on the biological implications of CALCR in the development of this type of cancer." (PMID 38985127, 2024). "Another pathway is the CALCR pathway with the ADM-CALCRL communication, the macrophages and cancer-associated fibroblasts signal the endothelial cells via ADM secretion, suggesting the promotion of angiogenesis." (PMID 39149248, 2024). "Intriguingly, we found several axes, such as NPBWR2-NPW or CALCR-CALCB, associated with lower survival more significantly than considering interaction partners alone in multiple cancer types." (PMID 38723607, 2024). "As a member of GPCRs, CALCR binds to its ligand and calcitonin and regulates a variety of downstream signaling pathways, thus regulating bone metabolism, calcium flux, and cancer cell proliferation." (PMID 35422890, 2022). "However, the molecular role of CALCR in cancers, particularly RCC, remains poorly understood, with limited insight into its specific functions and implications in RCC." (PMID 38985127, 2024). "Our findings were consistent with the study of CALCR in the majority of human cancers." (PMID 38985127, 2024). "Understanding the role of CALCR in RCC may provide valuable insights for the development of targeted therapeutic approaches for this type of cancer." (PMID 38985127, 2024). "Thus, the patients with cancer with high expression of CALCR and low expression of PTH1R may benefit from immunotherapy." (PMID 35252217, 2021). "It should be noted that Calcitonin and CALCR co-expression was observed in PC3M cells, which enhanced the invasiveness in this cancer context." (PMID 38985127, 2024). "We first determined the expression of CALCR in RCC using a human tissue chip containing 79 of RCC tissues and 73 of normal para-carcinoma tissues by IHC analysis." (PMID 38985127, 2024). "As the IHC figures shown, CALCR was markedly upregulated in RCC tissues, especially in advanced RCC tissues, compared with normal para-carcinoma tissues (para-carcinoma vs. stage I, P < 0.001; para-carcinoma vs. stage III, P = 0.004; para-carcinoma vs. stage IV, P < 0.001)." (PMID 38985127, 2024).
adeno-carcinoma (1 paper, 2012). "Finally, to assess whether the CalcR could serve as a receptor or co-receptor for virus entry in a non-permissive in vitro system, we utilized a rat adeno-carcinoma cell line (CRL-1666) that cannot be readily infected with HSV1 and transfected and infected it in the same way for HEK293T cells." (PMID 22761571, 2012).
CALCR also shares sentences with these, for which no sentence is quoted: diabetes (4 papers); infection (3); Anorexia (2); Arthritis (2); hypercalcaemia (2); metabolic disease (2); metabolic syndrome (2); thymic lymphoma (2); amyloid (1); Anxiety (1); bone cancer (1); brain tumour (1); Calcium nephrolithiasis (1); calcium oxalate kidney stones (1); cerebrovascular diseases (1); chronic pancreatitis (1); dental fluorosis (1); depression (1); depressive disorder (1); hypercalcemia (1); Hypercalciuria (1); Hypercholesterolemia (1); Hyperglycemia (1); Hyperinsulinemia (1); Hypertension (1); Impaired glucose tolerance (1); liver fibrosis (1); lymphoma (1); metastatic cancer (1); migraine with aura (1).
A further 12 diseases each share a sentence with CALCR in 1 paper.